KDM1A (lysine demethylase 1A)
Diseases named in the same sentence as KDM1A in open-access papers (continued):
Sharing a sentence is not in itself a finding about the gene and the disease.
leukemia (continued). "LSD1 (Lysine Specific Demethylase1)/KDM1A (Lysine Demethylase 1A), a flavin adenine dinucleotide (FAD)-dependent histone H3K4/K9 demethylase, sustains oncogenic potential of leukemia stem cells in primary human leukemia cells." (PMID 29156705, 2017). "Importantly, the inhibition of KDM1A in AML results in blast differentiation and leukemia progression blockage." (PMID 33167477, 2020). "Experimental mouse and human studies of MLL-AF9 leukemia have demonstrated that KDM1A-knockout cells differentiate efficiently and do not form colonies." (PMID 29921310, 2018). "Furthermore, these cyclopropylamine-based compounds do not exert toxicity, in contrast to many other KDM1A inhibitors, and hence, they may serve as useful therapeutics for MLL-rearranged leukemia cells." (PMID 29921310, 2018).
neuroblastoma (70 papers, 2011 to 2025). Neuroblastoma (NB) is the most common solid, extracranial childhood tumor. "This strategy demonstrates the potential to increase CAR T cell efficacy against high-risk neuroblastoma and potentially other solid tumors known to overexpress KDM1A." (PMID 34771652, 2021). "Overexpression of KDM1A in neuroblastoma is possibly linked to impaired KDM1A-silencing of microRNAs." (PMID 33029224, 2020). "The most common extracranial solid tumor of childhood (neuroblastoma) is associated with aberrant overexpression of KDM1A." (PMID 29921310, 2018). "We examined the role of the H3K4 modifying enzyme, KDM1A, in medulloblastoma, an enzyme also associated with malignant progression in the closely related tumor, neuroblastoma." (PMID 24252778, 2013). "High-level KDM1A expression in neuroblastomas is associated with an aggressive clinical course, and pharmacological inhibition of KDM1A significantly reduced growth of human neuroblastoma cell lines grown as xenografts in nude mice." (PMID 24252778, 2013). "However, more detailed investigations are required to understand the interaction between KDM1A and genes associated with neuroblastoma." (PMID 29921310, 2018). "LSD1/KDM1A expression is associated with poor prognosis in prostate, breast, lung, bladder, colorectal cancer and neuroblastoma." (PMID 40470182, 2025). "This phenotypical picture recapitulated the cellular phenotype we previously reported to be induced by KDM1A knockdown in neuroblastoma cell lines." (PMID 39458030, 2024). "Our experiments demonstrate that NCL-1 effectively inhibits KDM1A and suppresses the viability of aggressive neuroblastoma cells with various molecular drivers." (PMID 39458030, 2024). "NCL-1 induced neurite outgrowth in neuroblastoma cell lines that survived 72 h of treatment, as we previously observed following KDM1A knockdown, and upregulated known markers of neuronal differentiation." (PMID 39458030, 2024). "We have previously shown that KDM1A is strongly expressed in undifferentiated neuroblastomas, and correlates with poor patient prognosis." (PMID 39458030, 2024). "The results of this analysis indicate that LSD1/KDM1A peaks show preferential binding at the transcription start site (TSS) of the PRUNE-1 gene promoter in the human neuroblastoma cell line SH-SY5Y, a known neural model of differentiation." (PMID 38612726, 2024). "We previously showed that KDM1A is strongly expressed in undifferentiated neuroblastomas and correlates with poor patient prognosis, suggesting a possible clinical benefit from targeting KDM1A." (PMID 39458030, 2024). "This suppression of an aggressive neuroblastoma phenotype was concordant with that which we previously achieved via KDM1A knockdown in vitro and exceeded that of high-dose tranylcypromine treatment in vivo without the extreme adverse effects." (PMID 39458030, 2024). "We examined the effect of NCL-1 treatment in vitro on typical tumor cell functions in neuroblastoma cells and compared these cell phenotypes with the previously reported cellular phenotype induced by siRNA-mediated KDM1A knockdown." (PMID 39458030, 2024). "Pearson correlation analysis in two independent neuroblastoma cohorts consisting of 47 and 51 tumor samples demonstrated that KDM1A and FAS expression were negatively correlated." (PMID 34771652, 2021).
neuroblastoma (continued). "Overexpression of KDM1A has been reported in a variety of cancers including neuroblastoma, where the enzyme expression correlates with more aggressive disease." (PMID 34771652, 2021). "IMR-5/75 neuroblastoma cells, either untreated or pretreated with the KDM1A inhibitor, were incubated with an antibody that blocks FAS binding to its ligand without inducing FAS-directed cell death prior to exposure to CAR T cells." (PMID 34771652, 2021). "We inhibited KDM1A in the childhood tumor, neuroblastoma, to increase FAS expression on tumor cells." (PMID 34771652, 2021). "We showed that KDM1A inhibition in IMR-5/75 neuroblastoma cells induced FAS cell surface expression to higher levels than irradiation in a direct comparison." (PMID 34771652, 2021). "Untransduced control T cells and CAR T cells expressed much lower KDM1A protein levels than IMR-5/75 neuroblastoma cells." (PMID 34771652, 2021). "In line with a heterochromatic enrichment, protein expression of the demethylase KDM1A responsible for removing methyl groups from H3K9me337 was significantly lower in ALT-positive neuroblastomas compared to TERT-activated tumors." (PMID 33627664, 2021). "Analysis of public RNA-sequencing data from primary neuroblastomas revealed that a particular epigenetic modifier, the histone lysine demethylase 1A (KDM1A), correlated negatively with FAS expression." (PMID 34771652, 2021). "Here, we found that miR-542-3p was downregulated and KDM1A as well as ZNF346 were upregulated in neuroblastoma tissues and cells." (PMID 33987474, 2020). "Both overexpression of miR-542-3p and the knockdown of KDM1A suppressed cell proliferation and invasion in neuroblastomas." (PMID 33987474, 2020). "In summary, miR-542-3p inhibited cell proliferation and invasion through the downregulation of KDM1A in neuroblastoma." (PMID 33987474, 2020). "Taken together, our data established an association between miR-542-3p and KDM1A/ZNF346, and suggested that miR-542-3p suppressed cell proliferation and invasion via targeting KDM1A and ZNF346 in neuroblastoma." (PMID 33987474, 2020). "Present evidence suggests that KDM1A was highly expressed in various human cancers such as chondrosarcoma, rhabdomyosarcoma, neuroblastoma, prostate, bladder, breast, colorectal, gastric, and lung cancer." (PMID 33987474, 2020). "Inhibiting KDM1A in neuroblastoma cells increased H3K4 methylation, decreased cell proliferation, and reduced tumor growth." (PMID 33029224, 2020). "The overexpression of KDM1A has also been observed in a tumor closely related to neuroblastoma, i.e., medulloblastoma." (PMID 29921310, 2018). "High expression of KDM1A was observed in poorly differentiated neuroblastoma cells, and downregulation of KDM1A was found in differentiated neuroblastoma cells." (PMID 29921310, 2018). "For this, we used HCT116 cells and SK-N-BE neuroblastoma cells, as KDM1A is known to be highly expressed in neuroblastomas." (PMID 27449289, 2016). "Accordingly, LSD1/KDM1a is involved in maintaining the undifferentiated, malignant phenotype of neuroblastoma cells." (PMID 26062444, 2015). "All cell lines strongly expressed KDM1A, and the expression level was equivalent to the human neuroblastoma cell line, SK-N-BE, which was previously shown to express very high levels of KDM1A." (PMID 24252778, 2013). "Ferrari-Amorotti and colleagues found that KDM1A influences the motility and invasiveness of neuroblastoma and colon carcinoma cells." (PMID 24252778, 2013).
neuroblastoma (continued). "HUVEC-C cells express KDM1A, but to a lesser extent than in neuroblastoma cell lines." (PMID 39458030, 2024). "All three neuroblastoma cell lines expressed high KDM1A protein levels." (PMID 34771652, 2021). "Since KDM1A is overexpressed on neuroblastoma cells, it remains a tumor-specific approach." (PMID 34771652, 2021). "In addition, the transwell assay demonstrated that the cells transfected with si-KDM1A exhibited lower invasive ability than the cells transfected with si-NC in neuroblastoma." (PMID 33987474, 2020). "Furthermore, a new mechanism that miR-542-3p affecting neuroblastoma cell growth through modulating KDM1A and ZNF346 levels was confirmed." (PMID 33987474, 2020). "Based on these results, we speculated that miR-542-3p inhibited neuroblastoma cell development through the downregulation of KDM1A and ZNF346." (PMID 33987474, 2020). "It has been found that the microRNA miR-137 acts to suppress KDM1A expression in neuroblastoma." (PMID 29921310, 2018). "miR-137 is expressed at low levels in aggressive neuroblastoma tumors but directly targets KDM1A." (PMID 29921310, 2018). "MiR137 was also recently shown to regulate KDM1A in colon cancer and neuroblastoma." (PMID 26461474, 2015). "The chromatin-modifying enzyme lysine-specific demethylase 1, KDM1A/LSD1 is involved in maintaining the undifferentiated, malignant phenotype of neuroblastoma cells and its overexpression correlated with aggressive disease, poor differentiation and infaust outcome." (PMID 26062444, 2015). "Interestingly, comparing previously published expression data following KDM1A knockdown in neuroblastoma cells with expression data following KDM1A knockdown from this study suggested that KDM1A effects are specific for the tumor entity." (PMID 24252778, 2013). "The KDM1A small molecule inhibitor, NCL-1, reduced cell viability and proliferation and induced apoptosis in neuroblastoma cell lines with different molecular drivers of high-risk disease as well as mouse xenograft models derived from two neuroblastoma cell lines." (PMID 39458030, 2024). "Furthermore, KDM1A is a cofactor of the repressive function of N-Myc in neuroblastoma." (PMID 33462212, 2021). "Thus, KDM1A played pivotal roles in the progression of neuroblastoma development." (PMID 33987474, 2020). "Although MAOIs are very effective in vitro, and they did significantly suppress the growth of neuroblastoma xenograft tumors in mice, their lack of specificity for KDM1A requires treatment with high doses, which cause extensive side effects in whole animal testing models." (PMID 24252778, 2013). "In recent years, KDM1A and ZNF346 have been reported that they were closely related to neuroblastoma." (PMID 33987474, 2020). "Both KDM1A overexpression and ZNF346 upregulation weakened the effect of miR-542-3p on neuroblastoma cells." (PMID 33987474, 2020). "In this study, we confirmed that the overexpression of miR-542-3p suppressed cell proliferation, invasion, and tumor growth via the downregulation of KDM1A and ZNF346 in neuroblastomas." (PMID 33987474, 2020). "Our results suggested that miR-542-3p suppressed cell proliferation and invasion by targeting KDM1A and ZNF346 in neuroblastomas, providing a theoretical basis for the treatment of neuroblastoma." (PMID 33987474, 2020). "Whereas the levels of KDM1A and ZNF346 were increased in neuroblastoma tissues/cells compared to that in normal tissues/cells." (PMID 33987474, 2020). "Lysine-Specific Histone Demethylase 1A (LSD1) (also known as KDM1A and AOF2) cooperates with N-MYC to repress tumor suppressor genes, contributing to tumor maintenance in neuroblastoma." (PMID 28505071, 2017). "We have recently demonstrated involvement of KDM1A and H3K4 demethylation in the malignant progression of neuroblastoma, a challenging embryonal pediatric cancer sharing many morphological and molecular features with medulloblastoma." (PMID 24252778, 2013).
neuroblastoma (continued). "Blockade of FAS activity in the neuroblastoma cells eliminated the increase in tumor cell lysis observed in cells pretreated with the KDM1A inhibitor but did not impact CAR T cell-directed killing of untreated neuroblastoma cells." (PMID 34771652, 2021). "Therefore, miR-542-3p suppressed cell proliferation and invasion by regulating the levels of KDM1A and ZNF346 in neuroblastoma cells." (PMID 33987474, 2020). "For example, KDM1A promotes cell invasion through silencing the TIMP metallopeptidase inhibitor 3 (TIMP3) in non-small lung cancer, inhibits cell apoptosis in glioma, and promotes cell proliferation in neuroblastoma." (PMID 33987474, 2020). "Then, the levels of miR-542-3p, KDM1A, and ZNF346 in neuroblastoma tissues and cells was explored." (PMID 33987474, 2020). "Firstly, the levels of miR-542-3p, KDM1A and ZNF346 were determined in neuroblastoma." (PMID 33987474, 2020). "The specific and selective KDM1A inhibitor, NCL-1, may provide an avenue to reprogram aggressive neuroblastoma biology to a less proliferative and more differentiated state, and reduce hypoxia-associated pro-angiogenic pathways to disturb tumor vascularization." (PMID 39458030, 2024). "We next explored whether FAS upregulation by KDM1A inhibition was sufficient to kill even antigen-negative neuroblastoma cells via the FAS-FASL axis." (PMID 34771652, 2021). "FAS upregulation via KDM1A inhibition sensitized neuroblastoma cells to FAS-FASL-mediated killing and augmented CAR T cell therapy against antigen-poor or even antigen-negative neuroblastoma." (PMID 34771652, 2021).
gastric cancer (63 papers, 2013 to 2025). A primary or metastatic malignant neoplasm involving the stomach. "The low expression of KDM1A in gastric cancer was associated with poor PPS (p = 0.0013)." (PMID 34925656, 2021). "Capsaicin was shown to inhibit KDM1A/LSD1 with an IC50 of 0.6 ± 0.0421 μM in a gastric cancer cell line, indicating that capsaicin can effectively inhibit cancer cell proliferation." (PMID 40559396, 2025). "Other risk genes include KDM1A, a histone demethylase implicated in oncogenic chromatin remodeling, and ZFP36L1, an RNA‐binding protein associated with inflammation and gastric cancer development." (PMID 40561176, 2025). "As in vitro experiments confirmed that monobenzone inhibited KDM1A enzyme activity effectively, and KDM1A plays as a contributor in the migration of gastric cancer, we assessed the effects of monobenzone on the migration ability of gastric cancer cells." (PMID 33935733, 2021). "Notably, previous studies have shown that KDM1A is positively correlated with PD-L1 in cervical cancer tissues and gastric cancer specimens." (PMID 39638799, 2024). "All these studies indicated that monobenzone may be considered as a novel skeleton as KDM1A inhibitor for further optimization and used to inhibit gastric cancer cell migration." (PMID 33935733, 2021). "Mircetic and collaborators demonstrated that the histone lysine demethylase-1A (KDM1A) regulates the expression of NDRG1 in a gastric cancer (GC) organoid model through histone demethylation." (PMID 40332138, 2025). "In addition, increased expression of this lncRNA in gastric cancer patients can predict poor prognosis and promotes tumorigenesis by epigenetically silencing EphB3 (EPH receptor B3) via EZH2 and LSD1, also known as KDM1A (lysine demethylase 1A)." (PMID 32760219, 2020).